RN7SKP149 (RN7SK pseudogene 149)
Gene: Miscellaneous RNA gene on chromosome X (143,197,248 to 143,197,591, reverse strand). Ensembl gene ENSG00000199878.
Homologues: Orthologues: chimpanzee 7SK (92% identical), mouse Gm54559 (55% identical). Paralogues in human: RN7SKP146 (67% identical), RN7SKP162 (67% identical), RN7SKP176 (67% identical), RN7SKP180 (67% identical), RN7SKP189 (67% identical), RN7SKP127 (66% identical), RN7SKP230 (66% identical), RN7SKP165 (66% identical), RN7SKP86 (66% identical), RN7SKP124 (66% identical), RN7SKP79 (66% identical), RN7SKP171 (65% identical), and 283 more.